YAP1 (Yes1 associated transcriptional regulator)
Diseases named in the same sentence as YAP1 in open-access papers (continued):
Sharing a sentence is not in itself a finding about the gene and the disease.
tumor (continued). "YAP1 promotes the deposition of collagen VI (COLVI) in the tumor microenvironment." (PMID 40242775, 2025). "Furthermore, the broader significance of SFK inhibition extends to its interaction with the Hippo signaling pathway, where it can prevent the stabilization and nuclear localization of YAP1, a key modulator of tumor progression." (PMID 40362400, 2025). "Restoring the tumor-suppressive function of FAT1 or enhancing Hippo pathway activity could offer novel strategies for treating cancers driven by YAP1 activation." (PMID 41256331, 2025). "Yet, CAF plasticity also presents therapeutic opportunities: while pro-tumorigenic subtypes such as ECM CAFs, regulated by YAP1, accelerate cancer progression, anti-tumor subtypes such as Lym CAFs, driven by NF-κB signaling, can recruit and activate CD8+; T cells to restore immune surveillance." (PMID 41228234, 2025). "We found that YAP1 knockout blunted tumor growth and prolonged the survival of tumor-bearing mice." (PMID 38169595, 2024). "Whole genome and transcriptome sequencing of mucinous tubular and spindle cell RCC carcinomas (a rare cancer type) also revealed correlations between loss of Hippo pathway tumor suppressor genes such as NF2 and SAV1 and YAP1 nuclear accumulation during cancer progression." (PMID 39123485, 2024). "Notably, in a murine CRC xenograft model, miR-195-5p exhibited a substantial reduction in tumor growth by targeting and downregulating YAP1." (PMID 39431199, 2024). "Aberrant YAP1 activation is sufficient to induce tumor progression, including in LUAD59." (PMID 38355937, 2024). "As expected, YAP1-KD tumor weights were significantly less than the weights of the control clones." (PMID 39630608, 2024). "YAP1 is considered to be the root of tumor and is generally activated in human malignant tumors." (PMID 38550587, 2024). "YAP1 activation can induce growth-promoting traits, ultimately driving tumor progression." (PMID 39431199, 2024). "Inhibition of YAP1 is a potential strategy to reduce tumor lymph node metastasis." (PMID 38550587, 2024). "However, the tumour growth and YAP1 activation were significantly inhibited by AAV-shDAB2 in DAB2 high expression PDX2#." (PMID 38481347, 2024). "Thus, YAP1 plays a key role in tumor formation, and several studies have been conducted to suppress its expression." (PMID 39345743, 2024). "Interestingly, it was also found that miR-590 was negatively correlated with YAP1 expression NSCLC tumor tissues, and miR‐590 suppressed YAP1 expression by targeting its 3’ UTR in NSCLC cells." (PMID 38872189, 2024). "Here, we revealed that liver-specific developmental Sox9 elimination using Alb-Cre;Sox9(flox/flox) (LKO) and CRISPR/Cas9-based tumor-specific acute Sox9 elimination (CKO) in SB-HDTVI-based Akt-YAP1 (AY) and Akt-NRAS (AN) cHCC-CCA models showed contrasting responses." (PMID 39273023, 2024). "Furthermore, there is a significant correlation between the nuclear localization of YAP1 in primary tumors and tumor recurrence following the initial treatment." (PMID 38540274, 2024). "YAP1-NUT fusion was present in all NUT-positive neoplasms (n = 15)." (PMID 38891945, 2024). "Consistent with previous findings, genetic depletion of BAG3 led to a significant reduction in tumor sizes, an effect that could partially be mimicked with the two YAP1 inhibitors VK64 and VP." (PMID 38655699, 2024). "Furthermore, cytotoxic CD8+ T cells in the tumor spheroids of Yap1−/− mice also decreased compared to those in WT mice." (PMID 39198883, 2024). "However, in tumor cells, the Hippo signaling pathway is often inactivated, leading to excessive activation of YAP1." (PMID 38227081, 2024). "In addition to being highly expressed in numerous tumor cells, YAP1 is significantly expressed in Treg and CD8+T cells, inhibiting the immune response to tumors." (PMID 38550587, 2024).
tumor (continued). "In addition to tumor formation, they observed molecular characteristics of the YAP1–MAMLD1-driven tumor such as high expression of the radial glial neural stem cell marker PAX6, suggesting a transforming role of PAX6+ cells in ST-EPN–YAP1." (PMID 38469231, 2024). "Tumor progression and metastasis in a genetically engineered mouse model with a mutant c-Myc allele, was associated with transition from SCLC-A to SCLC-N subtype and in a subset of tumors to low-NE Yap1+SCLC." (PMID 39080761, 2024). "Western blotting showed that TET1 protein expression increased along with YAP1 expression in mst1/2 mutant mice tumor tissues, which suggests that TET1 expression may be regulated by YAP1 in HCC cells." (PMID 38967794, 2024). "The present study provides insights into novel link by which Yap1 signalling in tumor cells aids tumor progression through a direct, tumor cell–intrinsic, and a likely concomitant tumor cell–extrinsic mechanism involving the host’s anti-tumor immune response." (PMID 37957015, 2024). "The tumor growth curve, tumor mass, and gross images of isolated tumors clearly indicate that when WT MB49 cells were injected in the opposite flank of the YAP1-Sh clone (Sh-74 and Sh-77) site, the growth rate and tumor development were significantly attenuated." (PMID 39630608, 2024). "TBX5 and YES-associated protein 1 (YAP1) form a complex with β-catenin, which localizes and activates BCL2 Like 1 (BCL2L1) and Baculoviral IAP Repeat Containing 5 (BIRC5), thereby enhancing the anti-apoptotic effect on tumor cells." (PMID 38965548, 2024). "To further confirm that CSN6‐mediated tumor growth is YAP1‐dependent, we overexpressed YAP1‐5SA, a constitutive‐active YAP1, and found that YAP1‐5SA can rescue CSN6 KD‐mediated YAP1 target gene suppression, colony formation inhibition, and transcriptional attenuation." (PMID 38308184, 2024). "YAP1 is a transcription coregulator that plays a vital role in tumor progression." (PMID 38443336, 2024). "In addition, overexpression of the YAP1-S127A mutant significantly abolished PRRG2-mediated inhibition of tumor metastasis." (PMID 38355937, 2024). "However, the in vivo experimental results only provided preliminary evidence of autophagy and apoptosis in this tumor model, and the specific mechanism by which GL-V9 reduces YAP1 expression still needs further verification." (PMID 39458993, 2024). "In some tumor cells, MST1/2 and LATS1/2 may prevent phosphorylation of YAP1, causing its translocation to the nucleus, where it functions as a transcription factor that promotes proliferation, invasion, and metastasis." (PMID 39313797, 2024). "However, beyond this time point, although the overall tumor volume remained significantly less in the KD cells, the rate of growth of the YAP1-KD tumors rapidly increased when compared with tumor growth in immune-competent mice." (PMID 39630608, 2024). "Moreover, expression analysis of the T cell activation markers CD107 and IFN-γ indicated greater T cell activation in the YAP1-attenuated tumor tissues compared with controls." (PMID 39630608, 2024). "To validate whether our findings in cell line xenografts are representative of primary SMARCA4-UT tumors in patients, we initially made use of a YAP1 signature, previously used to interrogated YAP1 expression in SCLC Circulating Tumor Xenograft (CTX) models." (PMID 38180245, 2024). "In addition, aspects such as how ZFTA and YAP1 fusions function in tumor initiation and formation cannot be fully elucidated with in vitro models alone." (PMID 38469231, 2024). "A knockdown of YAP1 was further found to inhibit tumour growth." (PMID 39718433, 2024). "The transcriptional co-activator YAP1 has an important role in tissue development and homeostasis, and the activation of YAP1 is linked with the loss of function of a tumor suppressor NF2/Merlin, which enables tumor growth, invasion, and resistance to apoptosis." (PMID 39202270, 2024).
tumor (continued). "It is worth noting that YAP1 has different effects on tumor and peritumoral." (PMID 38550587, 2024). "In addition to gene mutations, heterogeneity in the expression of master genes also induces a competitive imbalance between tumor cells, such as c-Myc expression, Yap1 expression, and flower (FEW, also known as CACFD1) expression." (PMID 39872442, 2024). "However, a previous study has reported that YAP1 is extensively activated and promotes tumor cell apoptosis." (PMID 39308919, 2024). "YAP1 translocation to the nucleus showed micron dot distribution in tumor cells." (PMID 38550587, 2024). "Our data indicate that XMU-MP1 suppresses tumor metastasis in vivo, suggesting that YAP1 activation in macrophages may trigger a more potent antitumor immune response than its tumor-promoting effects." (PMID 39198883, 2024). "GA and VP are commonly used to investigate the functions of YAP1/TAZ in various developmental processes or tumor progressions, such as the proliferation of ovarian cancer cells, the reprogramming of colonic epithelium, and the homeostasis and repair of skin epithelium." (PMID 38540020, 2024). "This may suggest that DNMT1 and SOX9 are independently regulated under YAP1-driven HC-originated CCA tumor region, while the NRAS-SOX9-DNMT1 signaling cascade may be active in Akt-NRAS CCA tumor cells." (PMID 39273023, 2024). "Surprisingly, LATS1 phosphorylation of YAP1 may also indirectly promote the growth of a small population of cancer cells named tumor-repopulating cells (TRCs)." (PMID 38920690, 2024). "Moreover, we generated xenograft tumor models to measure the role of YAP1 and its phosphorylation in the regulation of metastasis in vivo." (PMID 38355937, 2024). "Moreover, the animal experiments corroborated these findings by revealing that YAP1 overexpression not only promoted tumor growth but also significantly reduced the survival rate of tumor-bearing mice." (PMID 38169595, 2024). "Notably, overexpression of PRRG2 or depletion of YAP1 markedly attenuated ectopic ZBTB11-induced tumor metastasis." (PMID 38355937, 2024). "As such, the loss of CAFs is not considered to be a major factor responsible for the tumor weight loss caused by YAP1 ablation in CAFs." (PMID 38308096, 2024). "YAP1 expression is inversely correlated with the prognosis of tumor patients." (PMID 38550587, 2024). "The latest study showed that impaired degradation of two proteins, the transcriptional co-activator YAP1 and IL6ST (interleukin six cytokine family signal transducer), by CMA promotes tumor growth, and it demonstrated that YAP1 and IL6ST are novel substrates for CMA." (PMID 37509689, 2023). "Additionally, the cCREs in these genes show high signal in the RELA-driven tumor and low signal in the YAP1-driven tumor." (PMID 37739938, 2023). "Considering the pro-tumor role of SNHG15/miR-200A-3p/YAP1/Hippo axis, combined targeting of the YAP1/Hippo signaling pathway might offer a promising treatment direction for PTC." (PMID 37056344, 2023). "Osimertinib treatment on mice further blocked the xenograft growth with YAP1 knocked down, indicating that knockdown of YAP1 could sensitize PC-9/AR tumor to osimertinib." (PMID 37215986, 2023). "We observed that mRNA levels of YAP1 and Notch3/4 were upregulated in 3D cultured tumor cells." (PMID 37369642, 2023). "In addition, Ki67 and YAP1 expression levels were observed using immunohistochemistry in orthotopic xenograft tumor mice." (PMID 38505381, 2023). "YAP1 is a transcriptional co-activator and correlated with tumor progression and radioresistance." (PMID 38065955, 2023). "Notably, we only observed a marginal effect of PA treatment on tumor volume of Yap1;TazDKO mice, again indicating a dependence of the PA-induced tumor-killing effect on the Hippo regulon." (PMID 36921037, 2023). "Furthermore, YAP1 expression was significantly related to larger tumor size, advanced tumor stage, tumor focality, lymph node metastasis, and extra-thyroidal extension." (PMID 37383164, 2023).
tumor (continued). "Correspondingly, GPRC5A and YAP1 had similar expression patterns in tumor tissues." (PMID 36735162, 2023). "As YAP1 is heterogeneously expressed across the tumor, we might have missed the YAP1-positive area in low-YAP1 tumors." (PMID 37894401, 2023). "Moreover, the results of in vitro and in vivo experiments suggested that YAP1 promoted drug resistance, tumor growth, and progression in SCLC." (PMID 37752152, 2023). "This study uncovers miR-141 as an OvCa-derived exosomal microRNA mediating the tumor-stroma interactions and the formation of tumor-promoting stromal niche through activating YAP1/GROα/CXCRs signaling cascade, providing new insight into therapy for OvCa patients with peritoneal metastases." (PMID 36624516, 2023). "It is important to note that the soma-germ transition induced by MS also coincided with inactivation of the Hippo tumor-suppressor pathway and the transition of YAP1 in the cell nucleus, colocalising and activating TEAD1, along with the nuclear activation of OCT4A." (PMID 36834647, 2023). "Further analysis showed that CENPK regulates the growth of tumor cells through YAP1." (PMID 37370088, 2023). "Furthermore, it has recently been reported how Yes-associated protein 1 (YAP1) can convert normal fibroblasts into CAFs in the PCa TME and can support the functional cross-talk between tumor cells and CAFs." (PMID 36899938, 2023). "The Hippo signaling pathway might be dysregulated in the miR-135b-5p-high group because of the high expression of YAP1, which might be related to the poor differentiation of tumor cells in this group." (PMID 36755690, 2023). "The phosphorylation of YAP1 was observed to be associated with platelet-mediated protection from anoikis, implicating that the activation of YAP1 in the signalling pathway results in the expression of a pro-survival gene signature, promoting tumour survival and metastasis." (PMID 38106409, 2023). "Targeting YAP1 and PD-L1 further reinforced the anti-tumor immunity." (PMID 37752152, 2023). "Furthermore, the expression of EMT genes and oncogenes, including Mmp3, Mmp7, Mmp8, Fn1, Vim, Foxc2, Ctnnb1, Lgr5, Axin2, cMyc, Ccnd1, and Yap1, was significantly high in the tumor of cohoused Nlrp12–/– compared with WT mice." (PMID 37581937, 2023). "Interestingly, tumor samples that showed nuclear MUC13 expression also demonstrated higher YAP1 expression." (PMID 37793774, 2023). "Considering the key role of the MT3-YAP1 axis in regulating OSCC chemotherapy resistance, it might be feasible to retard tumor growth by suppressing YAP1." (PMID 38041044, 2023). "Based on our findings and others’, we speculate that WWP2-mediated LATS1 ubiquitination and subsequent YAP1 activation may promote tumor progression, thereby providing novel targets for clinical cancer therapy." (PMID 36803368, 2023). "Overexpression of YAP-1 was detected in stromal spindle cells within the tumor microenvironment." (PMID 37476371, 2023). "Notably, YAP1 has been found to suppress tumor growth in vitro and in vivo by reprogramming intestinal stem cells." (PMID 37838732, 2023). "Studies have found that YAP1 inhibitors reduce the expression of PD-L1 in tumor tissues, promote the infiltration of CD8 T cells and CD4 T cells into tumor tissue, which disrupt the immunosuppressive microenvironment of cancer and improve the efficacy of HCC treatment." (PMID 38155974, 2023). "The transcriptional coactivator YAP1 (Yes1 associated transcriptional regulator) and IL6ST (interleukin 6 cytokine family signal transducer)-JAK (Janus kinase) signaling axis have a prominent role in tumor formation and growth, promoting cancer cell survival, proliferation, migration and metastasis." (PMID 35435804, 2023). "YAP1 is considered an oncogene associated with EMT, tumor cell proliferation, and metastasis." (PMID 36835505, 2023).
tumor (continued). "Our results illustrate that the interaction between Gankyrin and YAP1, which regulated glycolysis in tumor cells, may be a novel opportunity for the treatment of NSCLC in the future." (PMID 35810157, 2022). "Regression analyses showed that YAP1 expression was significantly increased along with tumor stiffness, and YAP1 positivity showed a positive correlation with maximal elasticity value, which supports previous in vitro studies regarding YAP1 activation via matrix stiffness." (PMID 36291755, 2022). "YAP1 is the core effect factor of this pathway and the focus of tumor development at present." (PMID 35350840, 2022). "Therefore, many findings have suggested that suppressing YAP1 can impede tumour proliferation and migration." (PMID 35264157, 2022). "Striatin 4 was recruited by SV40 ST to the Striatin Interacting Phosphatase and Kinase (STRIPAK) complex that redirects PP2A function toward the dephosphorylation of MAP4K4, leading to the activation of YAP1 and the inactivation of Hippo tumor-suppressive function." (PMID 36328247, 2022). "YAP1 binds to TEADs to facilitate the expression of tumor-promoting genes, and YAP1 may switch to bind to TP73 to promote apoptosis of cancer cells." (PMID 36479120, 2022). "We found that high expression of YAP1 was negatively correlated with the WHO grade and survival rate, indicating that YAP1 may contribute to tumor proliferation and invasion." (PMID 35350840, 2022). "Another study confirmed that YAP1 attenuated CD8+ T cell-mediated anti-tumor response." (PMID 36479120, 2022). "Nevertheless, YAP1 was also found to be a tumor suppressor gene." (PMID 35656547, 2022). "YAP1 functions as an oncogene, and its hyperactivation leads to various tumor-promoting effects." (PMID 35773411, 2022). "Interestingly, the combination of YAP-1 inhibition (verteporfin) and autophagic activation (rapamycin) attenuated tumor growth." (PMID 35884592, 2022). "Indeed, targeting YAP-1 has been shown to restore immune destruction of tumor cells, further potentiating the effectiveness of immunotherapy." (PMID 36359354, 2022). "In conclusion, both Gankyrin and YAP1 play important roles in tumor metabolism, and Gankyrin-targeted inhibition may be a potential anti-cancer therapeutic strategy for NSCLC." (PMID 35810157, 2022). "Based on the current study and previous research 39, we successfully demonstrated that miR-195-5p could abrogate the effect of the SNHG16/YAP1 axis on tumor progression." (PMID 36147462, 2022). "This implies that disruption of the basement membrane and direct contact between tumor cells and stroma might play a role in YAP1 activation." (PMID 36291755, 2022). "Of note, YAP1 also functions as a tumor corepressor to repress the expression of downstream genes, including the cell-cycle kinase inhibitor p27, by recruiting the NuRD (nucleosome remodeling deacetylase) complex, YY1, or EZH2, a polycomb repressive complex member." (PMID 36479120, 2022). "Inhibition of the Hippo pathway or overexpression of YAP1 may lead to the nuclear translocation of YAP1, which then binds to transcription factors to promote the expression of tumor-promoting genes." (PMID 36479120, 2022). "Dysregulation of the Hippo pathway and its downstream effector protein YAP1 in tumor samples could be prognostic markers to predict progressive cancers." (PMID 35407556, 2022). "GPER stimulation activates yes-associated protein 1 (YAP1) and transcriptional coactivator with a PDZ-binding domain (TAZ), two homologous transcription coactivators and key effectors of the Hippo tumor suppressor pathway, via the Gαq-11, PLCβ/PKC, and Rho/ROCK signaling pathways." (PMID 36558071, 2022). "Furthermore, YAP1 promoted tumor stemness maintenance partly by acting as a transcriptional coactivator to promote TEAD2-induced SOX2 expression." (PMID 35864972, 2022). "Finally, we revealed that YAP1 significantly promoted tumor progression and that SNHG16 rescued the effect of YAP1 on tumor progression." (PMID 36147462, 2022).